ATM (ATM serine/threonine kinase)
Diseases named in the same sentence as ATM in open-access papers (continued):
Sharing a sentence is not in itself a finding about the gene and the disease.
cancer (continued). "The analysis of the TSG promoters‘ methylation level of standardized CpG islands in cancer tissue revealed significant decreases of ATM, PTEN, and TIMP3 genes after sumac treatment." (PMID 33375383, 2020). "ATM is a well-recognized tumor suppressor and its alterations are common in several cancers including breast, gastric, colorectal, and prostate cancer." (PMID 32932697, 2020). "Another dysregulated protein in our data, high mobility group AT-hook 2 (HMGA2), promotes ATM expression and promotes cancer cell resistance to genotoxic agents." (PMID 33251127, 2020). "Inhibition of the catalytic activity of ATM for the treatment of cancer has been a target for antineoplastic based drug discovery." (PMID 32973968, 2020). "For example, the dependence of many cancer cells specifically on the G2/M checkpoint has led to the development of agents that target this checkpoint, particularly Chk1, Wee1, ATM, and ATR." (PMID 32117972, 2020). "We sequenced five patient samples harboring various amounts of positive cancer cells carrying the same ATM gene deletion and previously explored with conventional cytogenetics (karyotype and FISH)." (PMID 32049956, 2020). "ATM inhibitors are emerging as candidate cancer therapeutics based on their effects on the increased hypersensitivity to irradiation of ATM-deficient cells." (PMID 32157166, 2020). "The central DNA damage signaling proteins DNA-dependent protein kinase (DNA-PKcs), ataxia telangiectasia mutated (ATM), and ataxia telangiectasia and rad-3-related (ATR) kinases have become promising targets in cancer therapy." (PMID 32796846, 2020). "It is not worthy that further clarification will require systematic and in-depth understanding of platinum sensitivity and ATM-aberrant cancers." (PMID 30975222, 2019). "Mutations in six genes (NCOR1, GATA3, CDH1, ATM, AKT1, and PTEN) were significantly correlated with the corresponding expression levels, and were enriched and involved in multiple cancer‐related pathways." (PMID 30883028, 2019). "In our analysis, we found that seven out of 10 pedigrees had potential co-segregated pathogenic variants in known cancer-associated genes, including CHEK2, ATM, MRE11, and CTR9, and some other cancer-associated genes, such as IGF2R and CHRNA3." (PMID 31214250, 2019). "Genetic alterations and overexpression of ATM have been described for several cancer types, including BTC." (PMID 30813586, 2019). "Ataxia-telangiectasia mutated (ATM) and ataxia-telangiectasia related (ATR) kinases are key regulators of the DDR which are frequently deregulated in cancer." (PMID 30935402, 2019). "However, the cancer risk of PVs in ATM may still be debatable." (PMID 31882575, 2019). "Bioinformatics analysis revealed that SNPs in six genes (NCOR1, GATA3, CDH1, ATM, AKT1, and PTEN) were significantly associated with the corresponding expression levels and were involved in multiple pathways involved in cancer development." (PMID 30883028, 2019).
cancer (continued). "ATM signalling is a crucial biological pathway by which the cancer cell mediates its response to double-stranded DNA breaks and enacts DNA repair." (PMID 30763338, 2019). "Potentially pathogenic variants were found in five Cancer Gene Census germline genes: GALNT12, POLE, MPL, ATM, and ERCC4." (PMID 30886832, 2019). "Overall, our data demonstrate that combined loss of expression of ATM and heterozygosity of SMG1 results in more rapid cancer development particularly haematopoietic cancers." (PMID 31565865, 2019). "In the 20 cases analyzed, we detected three fusion events in known cancer driver genes (ATM in LUSC2; PTEN in LUSC1; WHSC1 in LUSC1), and a further seven events in candidate tumor-suppressor genes, including BOD1, DLG2, MBD2, and RBL1." (PMID 30348992, 2019). "Several studies have shown that ATM expression is associated with EMT and metastatic potential of cancer cells." (PMID 30961670, 2019). "These radioresistant cancer cell lines also displayed constitutively elevated levels of DSBs, as measured by H2AX and ataxia telangiectasia mutated (ATM) phosphorylation, relative to those in parental cell lines." (PMID 31799186, 2019). "Both the initial compound, TR100, and the improved compounds ATM-1001 and ATM-3507 have significant anti-cancer activity and synergize with anti-microtubule drugs." (PMID 31375704, 2019). "ATM rs189037 (G>A), located at the 5′UTR of its promoter, is an important variant reportedly involving susceptibility to several cancers, but results remain inconclusive." (PMID 31201228, 2019). "Hypoxia has been described to drive misregulation of DNA repair and damage response genes, such as Ataxia Telangiectasia mutated (ATM) or ATRX, in cancer cells, and has been shown to increase rates of mutations due to intracellular ROS production." (PMID 31861671, 2019). "For this, we used inhibitors of ATM and DNA-PK that are being developed as potential therapeutics for the treatment of cancer." (PMID 31036006, 2019). "This suggests that RDGVs in NSD1 are causally implicated in ~0.72% of cancers, a similar magnitude of effect as we observe for the well-known cancer predisposition genes BRCA1 (0.64%) and ATM (0.68%)." (PMID 29973584, 2018). "Cancers harboring mutations in “BRCAness” genes, including BRCA1, BRCA2, ATM and PALB2, have been found to be sensitive to DNA crosslinking agents." (PMID 29515757, 2018). "So, it is observed that such a phase space analysis of Wip1 and ATM dynamics provides a tool to manipulate the cancer cells pharmacologically." (PMID 29337287, 2018). "Significantly, inhibiting the pro-survival ATM–Akt pathway resulted in (i) enhanced anti-cancer activity (S)-crizotinib; (ii) enhanced anti-tumor activity of (S)-crizotinib in the xenograft GC mice, and (iii) re-sensitized resistant cells to (S)-crizotinib." (PMID 29855474, 2018). "In particular, ATM has a key role in maintaining genomic integrity and it is hypothesized that early loss of ATM function in the process of malignant transformation could be responsible for the generation of a mutator phenotype, an “enabling feature” in the growth of cancer." (PMID 30172261, 2018).
cancer (continued). "Taken together, this work documents diverse determinants of CTL levels across different cancer types and identifies ATM as a potential novel driver of CTL infiltration." (PMID 29615613, 2018). "RIDDLE cells, however, display normal levels of homologous recombination and functional ATM-mediated cell-cycle checkpoint, potentially protecting patients from cancer." (PMID 29584802, 2018). "The findings indicated that (S)-crizotinib, while harboring anti-cancer growth activities, also activated the ATM–Akt pathway for cell survival and DNA repair." (PMID 29855474, 2018). "The most commonly mutated cancer susceptibility genes were BRCA2 (n = 31), BRCA1 (n = 22), ATM (n = 19), and MUTYH (n = 19)." (PMID 29684080, 2018). "Since p-ATM functions in DNA injuries or genome instability, it is a marker of cancer cell DNA damage." (PMID 30598998, 2018). "Several ATR and ATM inhibitory compounds have been explored as therapeutic alternatives for cancer treatment, either as chemo- or radiosensitizers, or individually through synthetic lethality." (PMID 30265735, 2018). "Using total ATM levels from RPPA to approximate phosphorylated ATM, we analyzed how well ATM correlated with CTL score and compared this with neoantigen correlations across 13 different cancer types with sufficient matched data for RPPA, mutations, and RNAseq." (PMID 29615613, 2018). "We found that samples displaying a high percentage of ZEB1-positive cells exhibited a high level of ATM expression, whereas cancers exhibiting lower ZEB1 levels showed diminished ATM expression." (PMID 29352223, 2018). "Of note, proliferating leukemic Jurkat cells, used as control showed radiosensitization upon ATM inhibition, implying that ATM has different roles in IR-induced cell death in cancer vs. primary cells." (PMID 30323167, 2018). "Of note, ATM has been suggested to undergo selective pressure for inactivation in cancer, while loss of ATM function correlates with the occurrence of malignancies; this could explain how genetically unstable cells might escape this control mechanism, leading to cancer emergence." (PMID 29294106, 2018). "To understand immune invasion in these cancers, we developed an integrative multi-omics framework, identifying the DNA damage response protein ATM as a driver of cytokine production leading to increased immune infiltration." (PMID 29615613, 2018). "Three of the pan-cancer PTV-ALFRED genes (BRCA1, BRCA2, and ATM) and all four individual cancer type PTV-ALFRED genes were individually significantly enriched for rare PTVs in cases versus controls (nominal P < 0.05)." (PMID 29973584, 2018). "Above all, the findings strongly suggest that the activated ATM–Akt pathway was countering/masking anti-cancer activity of (S)-crizotinib in the GC." (PMID 29855474, 2018). "In vitro, it has been shown that inhibition of ATM or ATR can sensitize cancer cells to genotoxic agents, highlighting their potential as therapeutic targets." (PMID 29757235, 2018).
cancer (continued). "Among the many DDR proteins, ATM was shown to play a pivotal role in suppressing cancer development." (PMID 28337983, 2017). "ATM inhibitors sensitize various cancer cell lines and tumors in vitro and in vivo to radiation treatment." (PMID 29238697, 2017). "Tumor irradiation also induces TGF-β and IL-6 expression, thereby triggering the ATM-dependent DNA damage response and repair pathway in cancer cells." (PMID 28928376, 2017). "In this paper, we unveiled a novel role of Cdc7-Dbf4 in the regulation of ATR/ATM checkpoint signaling and HR DNA repair in cancer by phosphorylating HSP90 at S164." (PMID 29209046, 2017). "One important implication for our discovery of spDSB-induced tumorigenicity and cancer cell stemness pathway is translational: it provides a strong, mechanism-based rationale for targeting the ATM/ATR pathway in cancer treatment." (PMID 28337983, 2017). "Due to their radio- and chemo-sensitizing effects, ATM inhibitors are in pre-clinical and clinical trials as anti-cancer therapeutics." (PMID 29238697, 2017). "ATM inhibitors were initially developed as adjuvant agents for radiotherapy because of the perceived benefits in enhancing radiation sensitivity of cancer cells." (PMID 28337983, 2017). "Further, persistent ROS are shown to induce chronic activation of ATM that triggers a continuous activation of NF-κB pathways, contributing to aggressive phenotype of cancer cells." (PMID 28603525, 2017). "A variety of ATM inhibitors are currently in pre-clinical and clinical trials for multiple cancer types." (PMID 29238697, 2017). "In patient 1, mutations in ATM and GNAS, as well as a deletion in the tumor suppressor gene PTEN, likely led to tumorigenesis since they are potential cancer driver genes." (PMID 29169336, 2017). "Mutations in the PALB2 gene, along with other germline mutations, such as BRAC2, ataxia-telangiectasia mutated (ATM), etc., collectively alter the DNA repair pathway, resulting in increased accumulation of damaged DNA with eventual onset of cancer." (PMID 28383487, 2017). "Several COSMIC cancer genes were found to have various mutations in multiple samples, including PTEN, PIK3CA, BRCA2, and ATM." (PMID 28852190, 2017). "The emerging role of ATM in the regulation of autophagy is intriguing, although its impact on cancer progression has been poorly investigated so far." (PMID 28423511, 2017). "DNA damage caused by radiation, UV light, or anti-cancer agents results in phosphorylation of Histone γ-H2A.X at ser-139 by PI3K-like kinases, including ATM, ATR, and DNA-PK." (PMID 28157696, 2017). "We discovered that PD-L1 upregulation in cancer cells is ATM/ATR/Chk1-dependent after IR or treatment with CPT, APH or Etp." (PMID 29170499, 2017). "In other cancers, response to PARP inhibitors has been associated with defects in DNA damage response (DDR) (e.g., mutations in BRCA1/2, ATM)." (PMID 28212573, 2017). "The ATM-dependent DNA damage response contributes to the repair of DSBs in higher eukaryotic cells and cancer cells." (PMID 28928376, 2017).
cancer (continued). "To test this, we simultaneously knocked down both ATM and Mael in cancer cells and monitored cell survival." (PMID 27926513, 2017). "Somatic mutations of potential driver genes such as ARID1A, ATM, and MTOR promoted cancer growth, and many mutations were generated due to MMR deficiency." (PMID 28974240, 2017). "In other cancers such as ovarian and breast, mutations in HR genes (e.g., BRCA1/2, ATM) and/or elevated HRD scores (e.g., Myriad Genetics testing scores) predict patient response to PARP inhibitors." (PMID 28212573, 2017). "In particular, we showed that abrogating ATM function significantly impaired HER2-dependent tumorigenicity in vitro and in vivo also uncovering a novel cancer-related function of ATM as regulator of HER2 receptor stability." (PMID 28423511, 2017). "This review highlights what is currently known about ATM’s regulation of carbon metabolism, the implication of these pathways in cancer, and the development of ATM inhibitors as therapeutic strategies for cancer." (PMID 29238697, 2017). "Most unexpectedly, the self-inflicted DSBs lead to persistent and robust activation of ATM that sustains tumorigenicity and cancer cell stemness instead of suppressing them." (PMID 28337983, 2017). "This suggests that ATM-mediated regulation of AKT activity in cancer reprograms metabolism by increasing glucose uptake and potentially shifting metabolism from aerobic glycolysis to oxidative phosphorylation." (PMID 29238697, 2017). "Pharmacological inhibition of ATM has been shown to suppress Akt-mediated pro-survival signaling in cancer cells." (PMID 29152614, 2017). "Another study showed that Aurora-A and BRCA1/2 inversely controlled the sensitivity of cancer cells to radiotherapy through the ATM/Chk2-mediated DNA repair networks." (PMID 28404933, 2017). "ATM modulates carbon metabolism through many pathways that are essential for cancer development, survival, and therapeutic response." (PMID 29238697, 2017). "Nowadays, the development of small molecule inhibitors disrupting the functions of DNA repair proteins such as ATM, 53BP1 or DNA-PK is considered as an attractive therapeutic strategy against cancer radioresistance." (PMID 27563812, 2016). "Very recently, KIBRA has been found to interact with ataxia telangiectasia mutated (ATM), whose phosphorylation at T1006 is necessary for optimal DNA double-strand break repair in cancer cells." (PMID 27240404, 2016). "This new function of ATM expands the repertoire through which ATM functions as a tumor suppressor and has implications on DNA repair and cancer therapy." (PMID 27304073, 2016). "Considering the large size of the ATM gene (150 kb of genomic DNA) and the characteristic genomic instability of cancer cells, it is likely that a proportion of the occurring missense mutations are neutral passenger mutations." (PMID 27602502, 2016). "Cancers in which BRCA2, PALB2, or ATM have been biallelically inactivated are usually susceptible to poly(ADP-ribose) polymerase (PARP) inhibitors or platinum-based agents that facilitates double strand DNA breaks." (PMID 27732944, 2016). "For this reason, cancer therapies targeting ATM have been developed to increase the effectiveness of standard genotoxic treatments and/or to set up synthetic lethal approaches in cancers with DNA repair defects." (PMID 26901759, 2016). "This renders ATM unable to add phosphate groups to proteins, and so allows the cancer cells to continue proliferating even in the face of DNA damage." (PMID 27304073, 2016). "Phosphorylated forms of ATR (PS428-ATR) and ATM (PS1981 ATM) are expressed in cancer cells as a result of DNA damage." (PMID 27220670, 2016). "Defects in ATR-Chk1 and ATM-Chk2 signal transduction pathways are also key feature of several human cancers." (PMID 27442013, 2016).